CCR2 (C-C motif chemokine receptor 2)
Diseases named in the same sentence as CCR2 in open-access papers (continued):
Sharing a sentence is not in itself a finding about the gene and the disease.
aneurysm (8 papers, 2014 to 2025). Bulging or ballooning in an area of an artery secondary to arterial wall weakening. "CCR2+ macrophage tissue infiltration was associated with overall aneurysm deterioration, such as severe elastin degradation and increased MMP9 24 and MMP2 25 activity when compared to controls." (PMID 40365294, 2025). "MCP-1-directed aneurysm healing is eliminated by selective inhibition of MCP-1 or CCR2 and in MCP-1-deficient or CCR2-deficient mice." (PMID 29615957, 2018). "Although this is an early trend, this finding suggests more significant aneurysm growth in the high CCR2 subgroup." (PMID 40365294, 2025). "In summary, we found that inulin decreased pro-inflammatory Ly6Chi monocytes in the peripheral blood, aneurysm, and bone marrow and CCR2 expression on Ly6Chi monocytes from the peripheral blood." (PMID 40299521, 2025). "In AAA mice fed the inulin diet, the CCR2 expression of Ly6Chi monocytes from the peripheral blood reduced notably, yet remained unaltered in the aneurysm, bone marrow, and spleen." (PMID 40299521, 2025). "Everolimus, a rapamycin blocker, inhibited Ang II-induced aneurysm in ApoE−/− mice through diminished M1 polarization and suppressed the development of bone marrow CCR2 monocytes." (PMID 34489714, 2021). "MCP-1 eluting coils were implanted in our murine saccular aneurysm model in MCP-1 KO or CCR2 KO mice to determine the role of MCP-1 or CCR2 depletion on aneurysm tissue healing." (PMID 29615957, 2018). "Monocyte chemotactic protein-1 or CCR2 were selectively inhibited to determine their effect on aneurysm tissue healing." (PMID 29615957, 2018). "The chemokine receptors CCR2, CCR5, and CXCR3 are associated with pathways implicated previously in aneurysm pathogenesis." (PMID 24967416, 2014). "To further enhance the translational significance, we evaluated whether administration of CCR2 inhibitor RS504393 had therapeutic effects on established aneurysms." (PMID 39817456, 2025). "We propose that combinatory blockage of AT1R and CCR2 may result in selective β-arrestin inhibition while also preventing inflammatory cascades, having to a positive effect on aneurysm formation." (PMID 38732244, 2024). "Furthermore, there was significantly decreased tissue ingrowth in CCR2 KO mice compared with control: aneurysm tissue ingrowth in CCR2 KO was 4.6% versus WT control 56% (p < 0.0001, n = 6 and 10, respectively)." (PMID 29615957, 2018). "In addition, we validate that MCP-1 is in fact a critical cytokine in the aneurysm healing cascade by evaluating tissue-healing response with knockout (KO) or blockade of either MCP-1 or its receptor CCR2." (PMID 29615957, 2018). "Furthermore, it has been shown that the MCP-1 -CCR2 pathway plays a role in aneurysm development." (PMID 38732244, 2024). "Tissue ingrowth is also attenuated by systemic deficiency of both MCP-1 and CCR2 and delivery of systemic MCP-1 neutralizing antibody and CCR2 antagonist, further supporting the mechanistic role of MCP-1 mediated aneurysm healing." (PMID 29615957, 2018). "By inhibiting MCP-1 or its receptor CCR2, or by genetic KO of MCP-1 or CCR2, we eliminate the aneurysm tissue-healing response." (PMID 29615957, 2018). "Notably, surgical AAA patients demonstrated higher CCR2 signals irrespective of aneurysm size, linking elevated CCR2 activity to disease severity and aggressive inflammation." (PMID 40365294, 2025). "Consequently, although prospective follow-up demonstrated an early trend of increased AAA growth in the high CCR2 signal group, the lack of sufficient longitudinal aneurysm rupture outcome data limits the statistical significance of our findings." (PMID 40365294, 2025). "This suggests that CCR2 PET/CT may play an important role in identifying mechanical wall stress and instability independent of aneurysm size and diameter." (PMID 40365294, 2025).
aneurysm (continued). "Furthermore, an intragroup analysis of AAA surgical specimens collected from various regions of the aneurysm wall revealed a significant negative correlation (r = -0.85; P = 0.006) between DAB staining intensity of CCR2 and VVG-stained elastin fiber content." (PMID 40365294, 2025).
brain tumor (8 papers, 2018 to 2022). "In contrast to the immune potentiating effects of CCR2+HSCs, it is very interesting that the CCR2−HSCs that reach the intracranial brain tumor actually upregulate CCR2 expression along with markers of MDSCs including CD11b, Ly6G/C, and F4/80." (PMID 30333482, 2018). "CCR2+HSCs preferentially migrate to intracranial brain tumors and differentiate into antigen-presenting cells within the tumor microenvironment and cross-present tumor-derived antigens to CD8+ T cells." (PMID 30333482, 2018). "Here, the authors show that in brain tumors resistant to PD-1 blockade, HSCs expressing CCR2+ can reverse treatment resistance and sensitizes mice to immunotherapy." (PMID 30333482, 2018). "Our studies demonstrate a novel role for CCR2+HSCs in overcoming brain tumor resistance to PD-1 checkpoint blockade and adoptive cellular therapy in multiple invasive brain tumor models." (PMID 30333482, 2018). "Combination of CCR2+HSCs with adoptive cellular therapy also significantly extends survival in brain tumor-bearing mice." (PMID 30333482, 2018). "Furthermore, CCL2 and its related receptor (CCR2) play an important role in brain tumors and are involved in regulating the migration of monocytes into the vascular endothelium." (PMID 35370869, 2022). "Additionally, the APCs derived from CCR2+HSCs uniquely cross-present tumor-derived antigens to both endogenous and adoptively transferred T lymphocytes, leading to prolonged T-cell activation within brain tumors and enhanced tumor rejection." (PMID 30333482, 2018). "In the brain tumor, CD169+ macrophages expressed markers of monocyte-derived cells, such as CCR2 and Ly6C, although CD169 can be expressed in several tissue-resident macrophages." (PMID 36266311, 2022). "We found that relative to CCR2+HSC-derived cells, once in the brain tumor, cells that arose from CCR2−HSCs expressed significantly more CCR2 (p = 0.0035), F4/80 (p = 0.0138), and Ly6G/6C (p = 0.0001)." (PMID 30333482, 2018). "Seven days post transfer, brain tumors were harvested and HSC-derived cells were isolated and phenotyped for F4/80, Ly6G/6C, and CCR2." (PMID 30333482, 2018). "The APCs derived from CCR2+HSCs do not stay in the brain tumor, but extravasate into secondary lymphoid organs and cross-present tumor antigens to endogenous T cells." (PMID 30333482, 2018). "This knowledge, coupled with our observations of increased T-cell activation within brain tumors, led us to hypothesize that CCR2+HSC-derived cells found within the brain tumor are differentiating into antigen-presenting cells, thereby activating lymphocytes within the brain tumor microenvironment." (PMID 30333482, 2018).
cardiac hypertrophy (8 papers, 2020 to 2025). "This reduced fibrotic response may contribute to the observed preservation of left ventricular function and decreased hypertrophy in CCR2-deficient mice." (PMID 40257974, 2025). "Similar results have been reported in a model of early cardiac hypertrophy where resident macrophages were shown to inhibit fibrosis while the recruited monocyte-derived CCR2+ macrophages had the opposite effect." (PMID 38300872, 2024). "We could already show that in LV hypertrophy CCR2+ macrophages are likely to be expanded through CCL2 dependent monocyte recruitment." (PMID 40257974, 2025). "Furthermore, neutralizing antibody knockdown CCR2 in the bone marrow cells has effects on cardiac hypertrophy during Ang-II infusion and pressure overload." (PMID 32377427, 2020). "However, the CCR2+ macrophages which are engulfed in collagen-rich scar tissues are enriched for genes known to enhance cardiac hypertrophy and inflammation." (PMID 32377427, 2020). "The infiltrated CCR2+ macrophages expressing S00A8/A9 further amplify inflammation and aggravate the cardiac hypertrophy and dysfunction induced by chronic pressure overload." (PMID 40860162, 2025). "More distinctively, multiple genes of complement system are significantly upregulated in CCR2– CRMs during aging, and may serve as an amplification or initiation mechanism for local chronic inflammation in heart aging, which could lead to age-related myocardial hypertrophy and cardiac fibrosis." (PMID 38763956, 2024). "While Ccl7 plays a critical role in CCR2-dependent monocyte recruitment to the heart, MFGE8 is involved in cardiac hypertrophy, cardiac fibrosis, and removal of dead cells." (PMID 37563727, 2023).
epilepsy (8 papers, 2017 to 2024). A brain disorder characterized by episodes of abnormally increased neuronal discharge resulting in transient episodes of sensory or motor neurological dysfunction, or psychic dysfunction. "CD11b+ cells of GBM samples predominantly displayed down-regulation with respect to myeloid cells from epilepsy tissues, but two samples showed strong up-regulation of CCR2 in GBM." (PMID 32668709, 2020). "In pharmacoresistant epilepsy, CCR2 is highly expressed in neurons and monocytes suggesting that CCL2 and its receptor may play a role in epileptogenesis." (PMID 34512245, 2021). "In the context of epilepsy, CCL2 expression is robustly upregulated in human epileptic brain tissue, leading to the hypothesis that CCL2/CCR2 signaling may play a role in the pathogenesis and progression of epilepsy." (PMID 31717556, 2019). "Furthermore, we demonstrated that mGluR3, MCP1, and CCR-2 levels were not altered in all groups, suggesting a negative role in KA-induced epilepsy." (PMID 28386293, 2017).
hyperlipidemia (8 papers, 2014 to 2023). "Since hyperlipidaemia modulates monocyte subsets, and CCR2, CCR5, and CX3CR1 chemokine receptors mediate plaque monocyte recruitment, these were assessed by flow cytometry (Figure SIX)." (PMID 32667970, 2021). "In patients with hyperlipidemia, circulating monocyte CCR2 levels were significantly correlated with plasma LDL and cholesterol levels and were positively associated with monocyte inter-cellular lipid accumulation." (PMID 33184330, 2020). "In accordance, both CCL7 and its receptor CCR2, as well as CXCL1 have been implicated in monocyte mobilization from the bone marrow in steady state and under conditions of hyperlipidemia, respectively." (PMID 31641089, 2019). "In patients with hyperlipidemia, PCSK9 induces the expression of C-C chemokine receptor type 2 (CCR2) on the surface of monocytes and enhances their migration ability." (PMID 36970356, 2023). "To assess whether the MHC-IIhiCD11c+CD206- macrophages are monocyte-derived, we induced hyperlipidemia by PCSK9-AAV infection and WD feeding to Ccr2+/+ or Ccr2−/− mice." (PMID 36115863, 2022).
lung diseases (8 papers, 2005 to 2025). "With a follow‐up of up to 25 years, this report expands our understanding of lung disease in CCR2 deficiency and offers another monogenic cause of cystic lung disease." (PMID 40432300, 2025). "We describe a human lung disease caused by autosomal recessive, complete deficiency of the monocyte chemokine receptor C-C motif chemokine receptor 2 (CCR2)." (PMID 38157855, 2024). "Nevertheless, our results demonstrate that human inherited CCR2 deficiency leads to pulmonary disease, via a mechanism including insufficient numbers of alveolar macrophages, and predisposition to mycobacterial disease." (PMID 38157855, 2024). "Based on these findings, further investigations are warranted to understand the functional role of CCR2 on infiltrating lymphocytes in the setting of environmental exposure-induced lung disease." (PMID 38594676, 2024). "The possibility that MCP-1 and CCR2+ T cells are a general phenomenon of pediatric lung diseases seems very unlikely, since these markers were present only at low levels in BALF of children with severe allergic asthma." (PMID 16095529, 2005). "Thus far, CCR2+ T cells in BALF of patients with fibrotic lung diseases have not been determined." (PMID 16095529, 2005).
Myocardial fibrosis (8 papers, 2022 to 2025). "These genes were partially restored to WT levels in Dsg2mut/mut × Ccr2–/– mice, suggesting cross-talk between CCR2+ monocytes/macrophages and fibroblasts in the progression of myocardial fibrosis in Dsg2mut/mut mice." (PMID 38564300, 2024). "As seen in Dsg2mut/mut × IκBαΔN mice in which NFκB signaling in cardiac myocytes was blocked, Dsg2mut/mut × Ccr2–/– mice exhibited little if any myocardial fibrosis." (PMID 38564300, 2024). "Several studies have shown that CCR2+ macrophage accumulation promotes myocardial fibrosis and that the prevention of CCR2+ macrophage accumulation is associated with decreased myocardial fibrosis." (PMID 35327464, 2022). "Additionally, Dsg2mut/mut × Ccr2–/– mice displayed reduced myocardial fibrosis, yet equivalent cardiac function, compared with Dsg2mut/mut mice." (PMID 38564300, 2024). "Despite the distinct lack of myocardial fibrosis in Dsg2mut/mut × Ccr2–/– mice, LV contractile function was reduced to an extent seen in Dsg2mut/mut mice at 16 weeks of age." (PMID 38564300, 2024).
status epilepticus (8 papers, 2009 to 2023). Status epilepticus is defined as a continuous seizure lasting more than 30 min, or two or more seizures without full recovery of consciousness between any of them. "CCR2 is related to the regulation of other pro-inflammatory mediators and was shown to be required for production of IL-1β after convulsant-induced status epilepticus." (PMID 34512245, 2021). "CCL2-C-C chemokine receptor type 2 (CCR2) signaling has been shown to be crucial for monocyte-induced neuronal death after status epilepticus." (PMID 30759771, 2019). "In this work CCR2 and CCL2 expression were examined following status epilepticus (SE) induced by pilocarpine injection." (PMID 20034406, 2009). "Similarly, in the pilocarpine-induced status epilepticus rat model, the blockade of the MCP-1/CCR2 interaction with a selective CCR2 antagonist attenuated the ectopic migration of neuronal progenitors into the hilus." (PMID 24046730, 2013). "However, alterations to the expression patterns of CCL2 and CCR2 have not been examined following status epilepticus (SE) in a rat experimental model." (PMID 20034406, 2009).
abdominal aortic aneurysm (7 papers, 2023 to 2026). Enlargement and ballooning of the vessel that supplies arterial blood to the abdomen, pelvis and legs. "The CCR2/CCL2 molecular axis is a critical mediator of abdominal aortic aneurysm (AAA) pathogenesis." (PMID 41783018, 2026).
acute respiratory distress syndrome (7 papers, 2020 to 2025). Progressive and life-threatening pulmonary distress in the absence of an underlying pulmonary condition, usually following major trauma or surgery. "A recent animal study discovered that SARS-CoV-2-induced acute respiratory distress syndrome (ARDS) enhanced cardiac inflammation by enlarging the CCR2+ macrophage subset, potentially leading to cardiomyopathy." (PMID 40438117, 2025).
aortic aneurysm (7 papers, 2015 to 2025). A ruptured aneurysm located in the wall of the proximal portion of the descending aorta proceeding from the arch of the aorta. "It has been shown that IL-6 recruits CCR2-positive monocytes which serve to amplify the inflammatory cascade, and IL-6 signaling contributes to Angiotensin II-induced aortic aneurysm." (PMID 33175881, 2020). "Hence, this study also aimed to investigate if the combined inhibition of the AT1R and CCR2 may represent a therapeutic avenue for aortic aneurysm development." (PMID 38732244, 2024). "At more advanced stages, in Jak2V617F mutant mice with large aortic aneurysm, another dominant subset of macrophages expressing Ccr2, but not Lyve1, has been identified in the aortic wall." (PMID 36329047, 2022). "In addition, genetic deletion of the MCP-1 receptor C–C motif chemokine receptor 2 (CCR2), IL-6, or MMP-9 ameliorated aortic aneurysm pathogenesis." (PMID 29296021, 2018).
cardiomyopathy (7 papers, 2019 to 2023). A disease of the heart muscle or myocardium proper. "During the development of des-/- cardiomyopathy, Galectin-3 deficiency downregulated CCR2, Arg1 and pro-fibrotic gene expression as well as amelioration of poor cardiac remodeling, inflammation and failure." (PMID 36110847, 2022). "Similar to mice, cardiac CD45+CD64+CD14+ macrophages in patients with cardiomyopathy can also be categorized based on CCR2 and MHC-II (HLA-DR2) expression: CCR2−MHC-IIhi, CCR2+MHC-IIhi, and CCR2+MHC-IIlo subsets." (PMID 37858035, 2023). "Compared with WT controls, CCR2-KO mice had significantly preserved LVEF after ISO injection, conversely indicating a pathogenic role of monocytes in TTS-like cardiomyopathy." (PMID 35132957, 2022). "In our setting, CCR2−/− animals showed reduced F4/80+MHClo cardiac macrophage content and were protected from cardiomyopathy." (PMID 35090403, 2022). "In patients with cardiomyopathy, CCR2− Mφ seem to locate near the coronary vasculature, similarly to what has been reported for mice, whereas CCR2+ Mφ occupy fibrotic areas." (PMID 35406812, 2022). "In cardiomyopathy patients, CCR2− macrophages seem to locate near the coronary vasculature, similarly to what has been reported for mice, whereas CCR2+ macrophages occupy fibrotic areas." (PMID 31001541, 2019).
cognitive decline (7 papers, 2012 to 2025). "As such, mouse models of amyloidosis deficient in CCR2 exhibited exacerbation of cognitive decline and amyloid pathology; however, the role of CCR2/CCL2 axis in tauopathy was never substantiated." (PMID 34172073, 2021). "Moreover, transplantation of wild‐type bone marrow cells expressing CCR2 can decrease Aβ accumulation and prevent cognitive decline in the CCR2 KO AD mouse model." (PMID 36066198, 2022). "Furthermore, infiltrating monocytes are more robust in aged TBI mice compared with young TBI mice, and CCR2 KO prevents chronic injury‐induced cognitive decline in the aged TBI mice." (PMID 36066198, 2022). "Our findings are supported by a report from Naert and Rivest, who have linked the lack of Ly6Chi (CX3CR1low CCR2+ Gr1+) monocytes to cognitive decline in APPSwe/PS1 mice." (PMID 26984535, 2016). "In conclusion, low CCR2+ monocyte production by the hematopoietic system may be a direct biomarker of the cognitive decline in a context of AD." (PMID 23125823, 2012). "Genetic ablation of CCR2 in AD models reduces cerebral PMC numbers, whereas pharmacological CCR2 blockade exacerbates amyloid accumulation and cognitive decline." (PMID 40740772, 2025). "Human studies have shown that higher CCR2 expression correlates with poorer cognitive function, suggesting a direct involvement of CCR2 in human cognition, possibly due to enhanced CCL2 expression in brain microglia and macrophages, indicating a link to age-related cognitive decline." (PMID 39201480, 2024).